TNS2 (tensin 2)
Diseases named in the same sentence as TNS2 in open-access papers (continued):
Sharing a sentence is not in itself a finding about the gene and the disease.
tumor (11 papers, 2012 to 2025). "Immunohistochemical expression of TNS2 was compared with sex, age at diagnosis, primary tumor location, tumor size, mitotic count, metastasis status, tumor risk category, and mutation status." (PMID 35804982, 2022). "Further supporting this tumor-suppressive function, high TNS2 expression in human liver tissue inhibits proliferation and induces apoptosis in HCC cell lines through direct DLC1 interaction." (PMID 40906372, 2025). "In this study, we set out to explore the diagnostic value of TNS2 in GIST and its association with clinicopathological parameters such as metastases, mutation status, and tumor location." (PMID 35804982, 2022). "The stainings for TNS2 were heterogeneous in some tumors, but as we had three replicate TMA spots in each tumor, the risk of misevaluation of expression levels in tumors was minimized." (PMID 35804982, 2022). "The role of TNS2 in tumorigenesis is quite unclear, as it has been reported to promote cell migration and proliferation but also to contribute to the tumor-suppressive function via binding to the PTB domain of deleted in liver cancer 1 (DLC1) protein." (PMID 35804982, 2022). "The PTPase domain is critical for the de-phosphorylation of certain tyrosine kinases and for the tumor-suppressive functions of TNS2." (PMID 30419905, 2018). "Another possible tumor-driving pathway with TNS2 includes AXL, IRS-1, and GLUT4." (PMID 35804982, 2022). "For instance, the tumor suppressor DLC1 may interact with TNS2 and contribute to the growth-suppressive activity of DLC1 in hepatocellular carcinoma." (PMID 30419905, 2018). "Notably, low TNS2 expression correlated with poor overall prognosis in breast, lung, and bladder cancer cohorts and predicted inferior relapse-free survival in specific datasets, suggesting tumor-suppressive roles." (PMID 40906372, 2025). "Expression levels of the key genes TNS2, LRIF1, STK26, and TTF2 showed marked differences, exhibiting substantially elevated expression in tumor tissues versus normal tissues." (PMID 40212965, 2025). "In a detailed examination of 114 paired samples from the TCGA–LUAD cohort, significant variations were observed in the expression of LRIF1, STK26, TNS2, and TTF2 between tumor and normal tissues, with p values less than 0.001." (PMID 40212965, 2025). "A microscopic analysis demonstrated that positive expression of TNS1, TNS2 and TNS3 proteins in tumor cells was present in 7 (7.78%), 4 (4.44%) and 32 (35.56%) out of 90 patients, respectively." (PMID 33926026, 2021). "In tumor cells of all cases, we observed both membranous and cytoplasmic expressions of TNS1, TNS2, and TNS3 proteins." (PMID 33926026, 2021). "In the tumor tissue microarray, high expression levels (H-score 201—300) of TNS2, p-TNS2, Axl, and p-Axl were detected in the pancreatic ductal areas of 33 PDAC patients’ tumor tissues." (PMID 30419905, 2018). "Representative micrographs show the histopathologic features and the expressions of TNS2, Axl, IRS-1, and GLUT4 in tumor and the adjacent normal tissues by immunohistochemical analysis." (PMID 30419905, 2018). "TNS2 has been shown to dephosphorylate the insulin receptor substrate 1 (IRS-1) and decrease its activation, which in turn can lead to increased interaction between PI3K and PDGFRA, and thus, increased tumor growth." (PMID 35804982, 2022). "Indeed, a number of these genes have been identified as candidate tumor suppressor genes including CREBRF, DIXDC1, AHNAK and TNS2." (PMID 28122328, 2017). "We noted that the positive expression of TNS1 and TNS2 was not common in tumor cells, whereas the positive expression of TNS3 occurred in tumor cells of about one-third of GC patients." (PMID 33926026, 2021). "The role of TNS2 in GIST tumorigenesis or tumor suppression has not been researched yet, and due to being overexpressed in GISTs compared with other cancers, warrants functional studies on its possible tumor-driving or tumor-suppressing roles and modes of action." (PMID 35804982, 2022).
cancer (10 papers, 2016 to 2025). A tumor composed of atypical neoplastic, often pleomorphic cells that invade other tissues. "An RNA-seq analysis revealed a significant involvement of TNS2 in the formation of focal adhesions which are associated with the development of metastases in numerous cancers." (PMID 33926026, 2021). "In this study, we have clarified the identities of three human TNS2 isoforms and established the loss-of-function effects of TNS2 in cancer cells." (PMID 27203214, 2016). "The interaction of Axl and TNS2 could serve as a potential therapeutic target for the management of the IRS-1-associated cancer progression and other related diseases." (PMID 30419905, 2018). "We further speculate that the interaction of Axl and TNS2 could be a potential therapeutic target for the management of the IRS-1-associated cancer progression and other related diseases." (PMID 30419905, 2018). "Tensin2 (TNS2) was found to be downregulated in most human cancers but overexpressed in GIST; we therefore investigated the role of TNS2 as a diagnostic biomarker for GIST." (PMID 35804982, 2022). "TNS2 expression in GISTs was relatively close to the level of expression in healthy tissues but overexpressed in GISTs compared with most other cancers (Appendix A, Figure A1)." (PMID 35804982, 2022). "The median of relative expression of TNS2 is more than doubled in GISTs compared with most other cancers included in the IST Online database." (PMID 35804982, 2022). "TNS2 expression occurred more frequently in cancers with peritumoral inflammation (9.52% of patients) compared to tumors without inflammation in the surrounding tissues (0.00% of patients) (p = 0.041)." (PMID 33926026, 2021). "Accumulating evidence has demonstrated that TNS2 plays a role in regulating cell proliferation and migration, and it is downregulated in various cancers, including EOC, which enhances tumorigenicity." (PMID 33091877, 2020). "It is plausible that TNS2 conveys different signals by binding with different partners involved in cancer progression." (PMID 30419905, 2018). "A panel of human cancer cell lines was screened by immunoblot analysis to evaluate for TNS2 protein expression." (PMID 27203214, 2016). "Our TNS2 knockdown experiments have indicated the role of TNS2 in suppressing tumorigenicity of cancer cells." (PMID 27203214, 2016). "To determine the clinical relevance of TNS2 expression in cancer patients, we have searched and analyzed publicly available expression databases." (PMID 27203214, 2016). "Compared to TNS1, evidence elucidating TNS2 functions in cancer remains relatively limited." (PMID 40906372, 2025). "Thus, while knockdown of TNS1, 3 and 4 reduces proliferation in several normal and cancer cell lines, overexpression of TNS2 reduces the proliferation of several cancer cell lines." (PMID 37510408, 2023). "Many other cell adhesion molecules, including members of the Tensin family but not TNS2, have been linked to metastatic activity in cancers." (PMID 35804982, 2022). "In our research, we demonstrate that TNS2 serves as a substrate for Axl and may play a critical role in cancer by modulating Axl signaling." (PMID 30419905, 2018). "The Oncomine reference database was used to explore the effects of TNS2 in cancer cells." (PMID 30419905, 2018). "The Axl/TNS2/IRS-1 cross-talk may further potentially play a critical role in glucose metabolism of cancer cells." (PMID 30419905, 2018). "We investigated the possible mechanism of Axl-regulated cancer metabolism through TNS2 expression." (PMID 30419905, 2018). "Furthermore, using online survival analysis tools (PROGgeneV2 and Kaplan Meier-plotter), the correlation of low TNS2 expression with poor overall survival probability was analyzed in various cancer cohorts." (PMID 27203214, 2016).
cancer (continued). "Thus, we imply that MSI1 is responsible for modulating AKT phosphorylation through multiple indirect ways, including posttranscriptional down-regulation of Numb/PTEN and TNS2, and eventually achieve the survival of cancer cells under chemotherapy." (PMID 27285760, 2016). "On the other hand, overexpression of TNS2 V2 reduced BEL7402 cancer cell colony formation activity." (PMID 27203214, 2016). "Eight of these nine were consistently associated with clinical phenotypes, of which three exhibited statistical significance in both differential analyses between cancer and adjacent tissues, and survival analyses (FAM83E pS351, RREB1 pS161, and TNS2 pS830)." (PMID 39793886, 2025). "EGFRAP and PVRAP have been proposed to be orthologs of human TNS2 and TNS4 (FlyBase), proteins that in knockdown conditions increase tumorigenicity in several cancer lines." (PMID 34411095, 2021). "The expression levels of TNS2, Axl, IRS-1, PDK1 and Glut4 in human cancer cells were measured by Western blot and/or IP-Western blot assays." (PMID 30419905, 2018). "Silencing of TNS2 promotes the activation of IRS1, Akt, and Mek, and enhances cancer cell tumorigenicities." (PMID 27203214, 2016). "Knockdown of human TNS2 and TNS4 increases tumorigenicity in several cancer lines." (PMID 37510408, 2023). "This releases TNS2 from its binding partner IRS-1, which in turn upregulates Glut4 and PDK1, enzymes that may play a critical role in the glucose metabolism of cancer cells." (PMID 35804982, 2022). "By visually investigating the expression level of TNS2 in a transcriptome database, we found that the expression of TNS2 in GIST was close to that of healthy tissues, but highly overexpressed compared with other cancers." (PMID 35804982, 2022). "In our study, we observed statistically significant differences in TNS2 expression between cancers with and without a peritumoral inflammation." (PMID 33926026, 2021). "Our results revealed for the first time that Axl binds to and phosphorylates TNS2 and that Axl/TNS2/IRS-1 cross-talk may potentially play a critical role in glucose metabolism of cancer cells." (PMID 30419905, 2018). "The two key enzymes of aerobic glycolysis (Glut4 and PDK1) were found to be up-regulated by Axl/TNS2/IRS-1 cross-talk and may play a critical role in glucose metabolism of cancer cells." (PMID 30419905, 2018). "TNS2 inhibits AKT/PKB signaling via C1-TEN (C1 domain-containing phosphatase and TENsin homologue) and mediates TPO (Thrombopoietin)/c-Mpl pathway, which engages AKT signaling in induction of cancer growth." (PMID 27285760, 2016). "Its role in various cancer types is not definitively established yet; moreover, TNS2’s role in PDAC remains unknown." (PMID 30419905, 2018). "In the absence of TNS2, elevated IRS1 signaling may promote tumorigenicity in cancer cells." (PMID 27203214, 2016).
renal disease (3 papers, 2018 to 2023). "ICGN mice are a model of kidney disease involving the mutation of the tensin 2 gene." (PMID 31431054, 2019). "For instance, Trametinib, a Mek inhibitor, reduces the renal disease burden in Tns1-KO mice and dihydro-CDDO-trifluoroethyl amide, a bardoxolone methyl analog, suppresses tubular epithelial cell injury, chronic inflammation, and fibrosis, but not glomerular defects in ICGN mice with Tns2 mutation." (PMID 37374025, 2023).
infection (1 paper, 2021). The state of being infected such as from the introduction of a foreign agent such as serum, vaccine, antigenic substance or organism. "TNS2 expression was more frequently observed in tumors with H. pylori infection (13.64% of patients) than in cases without the infection (1.61% of patients) (p = 0.023)." (PMID 33926026, 2021).
TNS2 also shares sentences with these, for which no sentence is quoted: Hypertension (3 papers); type 2 diabetes (2); cholangiocarcinoma (1); diabetic kidney disease (1); esophageal squamous cell carcinoma (1); fibrosis (1); glomerulonephritis (1); head and neck squamous cell carcinoma (1); HIV-associated nephropathy (1); hypertrophy (1); Insulin resistance (1); kidney damage (1); liver cancer (1); lung adenocarcinoma (1); Obesity (1); preeclampsia (1); prostate carcinoma (1); schwannoma (1).